CTSS (cathepsin S)
Diseases named in the same sentence as CTSS in open-access papers (continued):
Sharing a sentence is not in itself a finding about the gene and the disease.
tumor (continued). "Dosing of compound 6 resulted in a reduction in tumor progression of approximately 50 % by day 16 when compared to vehicle-treated controls, an effect similar to what we had previously observed with CTSS depletion." (PMID 27097645, 2016). "Taken together these in vitro studies demonstrate that compound 6 could inhibit CTSS to block pro-tumorigenic characteristics of tumor and endothelial cells, warranting further investigation with in vivo models." (PMID 27097645, 2016). "CTSS has been shown to play a key role in neo-vascularisation at the tumor site." (PMID 27097645, 2016). "Similarly, targeting CTSS activities by using the specific monoclonal antibody Fsn0503 not only attenuates tumor invasion and HUVEC tube formation but also elicits strong antibody-dependent cellular cytotoxicity in tumor cells." (PMID 26029922, 2015). "The potential of cathepsin S as a novel cancer target amenable to antibody mediated therapy has been examined using a murine anti-cathepsin S monoclonal antibody (Fsn0503) which is capable of blocking tumor cell invasion, endothelial tube formation and microvascular sprouting during angiogenesis." (PMID 22168338, 2011). "In normal conditions, cathepsin S has limited tissue distribution and is found primarily in lysosomal compartments of professional antigen presenting cells; however it is up-regulated and secreted into the microenvironment during tumor development." (PMID 22168338, 2011). "Indeed, these findings are consistent with other findings in cathepsin S null mice which demonstrate impaired microvessel development and in tumour models, impaired tumour angiogenesis." (PMID 20824056, 2010). "In addition to CTSB, other CTSs have been proposed as participants in the angiogenesis and invasion of tumor cells." (PMID 20727192, 2010). "Interestingly, tumor cells are also able to increase the expression of cathepsin S, a protease that is predominantly expressed by leukocytes, to cleave the junctional adhesion molecules that maintain BBB integrity and thus help tumor cells to break down the BBB." (PMID 36765679, 2023). "Besides, the inhibition of cathepsin S-induced autophagy in tumor cells could increase the expression of microtubule-associated protein I light chain 3 (LC3) protein, which may then cause the cytoplasmic form (LC3-I) to be cleaved and lapidated into LC3-II." (PMID 37334378, 2023). "To assess whether an eQTL-informed approach could reveal potential cancer immunotherapy targets, we inhibit CTSS, a gene implicated by cancer risk and ICB response-associated polygenic models; CTSS inhibition results in slowed tumor growth and extended survival in vivo." (PMID 37173324, 2023). "Furthermore, our studies revealed that inhibition of cathepsin S by RJW-58 could retard tumor progression and metastasis." (PMID 33754020, 2021). "In addition, cathepsin S (Ctss) has been shown to be a relevant factor in the promotion of breast-to-brain metastasis, where experimental brain metastasis was only reduced by the combined depletion in macrophages and tumor cells." (PMID 32707827, 2020). "Furthermore, cathepsin S plays critical roles in tumor development." (PMID 30120227, 2018). "In summary, inhibition of Src kinase suppressed TNBC tumor growth and metastasis, and Src inhibitors such as BJ-2302 may constitute a novel therapeutic tool to treat breast cancer that expresses high levels of CTSS and MMP-9." (PMID 30185799, 2018). "However, cathepsin S is also expressed in epithelial cells and various malignant tumor cells." (PMID 29707130, 2018). "In summary, these results highlight the characterisation of this nitrile cathepsin S inhibitor using in vitro and in vivo tumor models, presenting a compound which may be used to further dissect the role of cathepsin S in cancer progression and may hold therapeutic potential." (PMID 27097645, 2016).
tumor (continued). "Given that we have previously observed that secreted cathepsin S enhances the invasion of tumour cells through the extracellular matrix, inducing a pericellular zone of proteolysis around the cells, we wished to ascertain whether a similar effect was seen in endothelial cells." (PMID 20824056, 2010). "Modulating these cleavage steps provides opportunities for intervention: inhibition of cathepsin S in malignant B cells alters antigen processing and MHC-II maturation, triggering anti-tumor immune responses and reducing tumor growth." (PMID 41439980, 2025). "The results of the IHC consistently showed lower CTSS expression, higher IL-7 expression, and more infiltration of CD8+ T cells in tumor tissue samples from the treatment groups than in the control group." (PMID 40707961, 2025). "Molecular studies on tumor tissues showed an increase in the local expression of IL-7 and the number of CD8+ T cells in the CTSS-knockdown group, which was counteracted by αIL-7." (PMID 40707961, 2025). "Two syngeneic OC mice models were utilized to investigate the anti-cancer effects and the tumor immunity modulation effects of RJW-58, a CTSS activity inhibitor, and the combination with the anti-PD-1 antibody." (PMID 40707961, 2025). "Cathepsin S cleaves junctional adhesion molecule B (JAM-B) at the blood–brain barrier (BBB), facilitating tumor cell transmigration specifically into the brain parenchyma." (PMID 41463352, 2025). "RNA was extracted from tumor tissue, and the expression of DEIRGs including GREM2, CTSS, TINAGL1, ACKR1, HLA-DRB1, and STC2 was verified using real-time quantitative reverse transcription PCR (RT-qPCR)." (PMID 39735532, 2024). "Review articles point out the involvement of cathepsin S (CTSS) in various processes, such astumour microenvironment remodelling, angiogenesis promotion, tumour migration and growth." (PMID 39712508, 2024). "Cathepsin S is produced by both macrophages and tumor cells and facilitates BBB extravasation through proteolytic degradation of the junctional protein JAM-B, with depletion of Cathepsin S via inhibitors significantly reducing brain metastasis in vivo." (PMID 37688612, 2023). "Third, BCG hydrogel mediated CTSS-dependent antigen processing and presentation and led to enhanced TCR diversity with increased frequencies of tumor-specific CD8+ T lymphocytes." (PMID 35732347, 2022). "Nevertheless, our findings indicate that BCG hydrogel treatment leads to increased TCR repertoire diversity and tumor antigen-specific TCR clones, resulting from enhanced CTSS expression and altered antigen processing and presentation in MΦ and DC." (PMID 35732347, 2022). "Extracellular matrix glycoproteins such as Laminin-γ2 and proteolytic enzymes such as MMP1, CTSS & CTSB were radically up-regulated under acute acidotic stress, but all become less expressed when tumor cells steadily adapted to extended extracellular acidity." (PMID 35410237, 2022). "Ultimately, we showed that the administration of a single dose of a cathepsin S-selective inhibitor LY3000328, which targets both tumor and stromal-supplied cathepsin S, was able to attenuate cancer pain for at least 12 h in two independent xenograft models." (PMID 34572924, 2021). "In the animals that overexpressed CTSS or the mutant CTSS, CD8+ T cells were prone to be eliminated and CD4+ T cells were highly infiltrated and colocalized with tumor B cells." (PMID 34069564, 2021). "Compared with PI3K inhibitors, suppression of CTSS not only decreased the PI3K signaling but also impaired the process of tumor angiogenesis and tumor growth." (PMID 33613746, 2021). "Our previous study has shown CTSS inhibition reduced Ca2+ influx through affecting SOCE activation and interfering STIM1 trafficking, which leads to the suppression of tumor cell progression." (PMID 33754020, 2021).
tumor (continued). "Cathepsin S, another protein of cysteine protease family, was reported to be related with more frequent LNM and advanced tumor-node-metastasis stages compared with the low-expression group." (PMID 33333840, 2020). "ERK signaling pathway can be activated by fisetin, which in turn down-regulates the expression levels of CTSS and ADAM9, thereby inhibiting cell proliferation, invasion and migration, and forming an anti-tumor metastasis effect." (PMID 32875951, 2020). "Our current study also demonstrated that although their effects were much weaker than BJ-2302, CTSS and MMP inhibitors (Z-FL-COCHO and batimastat) suppressed tumor growth in vivo." (PMID 30185799, 2018). "As VEGF is a major pro-angiogenic growth factor and up-regulated in many tumours; we stimulated growth factor starved HUVECs with VEGF and observed an up-regulation of the cathepsin S at the mRNA and protein levels." (PMID 20824056, 2010). "Functionally, JQ1 markedly improved tumor recognition by autologous MART-1- and neoantigen-specific CD8+ TIL, while dampening CD4+ TIL activation through the downregulation of Cathepsin S (CTSS)." (PMID 42057381, 2026). "In this in vivo model, CTSS knockdown resulted in increased infiltration of CD8+ T-cells expressing granzyme B along with enhanced autophagy markers and reduced PD-L1 expression in tumor cells." (PMID 40794185, 2025). "Although CTSS is upregulated in specific solid tumors, including CRC, its precise role in promoting tumor growth remains unclear." (PMID 40794185, 2025). "The analysis of two HNC databases, The Cancer Genome Atlas Program and the Gene Expression Omnibus (GEO No. GSE6791), revealed that the mRNA level of CTSS in tumor tissues was higher than that in normal tissues." (PMID 40707961, 2025). "Among these, CTSS was uniquely identified as the lysosomal protease capable of cleaving GSDMD, IL‐1β, and IL‐18 independently of caspase‐1, establishing a novel pathway of tumor‐specific pyroptosis induction." (PMID 40539828, 2025). "Cathepsin S degrades many extracellular matrix (ECM) proteins, such as fibronectin, laminin, collagens and elastin, promoting TME formation-related immune suppression and tumor growth." (PMID 38318188, 2024). "However, the expressions of IGKC, IGLC1, ITGB2, CTSS, HLA‐DPB1, and RSAD2 were elevated in tumor tissue and they served as protective factors." (PMID 37543714, 2023). "Since CTSS can be transferred to the extracellular matrix (ECM), it degrades diverse ECM proteins, including laminin, fibronectin, elastin, osteocalcin, and some collagens, thus promoting tumor invasion and metastasis." (PMID 33425712, 2020). "Not surprisingly, a number of proteins involved in tumor cell dissemination and BBB invasion were also found to associate with BCBM progression, including cathepsin-S, S100A4, RANKL, RANK, Src, HYAL1, HAS2 and prominin-1 (CD133)." (PMID 32110283, 2020). "However, a combination of the CTSS inhibitor 6r and the EGFR tyrosine kinase inhibitor Iressa synergistically promotes tumour cell apoptosis." (PMID 27387133, 2016). "Besides CTSB, other CTSs, such as cathepsin D (CTSD), cathepsin L (CTSL) and cathepsin S (CTSS), showed highly expression in invasive tumor and increase motility of cancer cells." (PMID 27031837, 2016). "In the present study, the expression of CTSS and CTSC was also detected in cancerous ovaries of hens, suggesting that CTSS and CTSC may also play roles in the angiogenesis and invasion of tumor cells." (PMID 20727192, 2010). "Therefore, the significant difference in T cell proliferation observed in the ex vivo study, by manipulating the CM of the CTSS-knockdown tumor with or without the IL-7 recombinant protein, pursued the interaction that occurred in the local tissue." (PMID 40707961, 2025). "Furthermore, immature forms of CTSs could be released from AML cells, transported via EVs and then activated in the tumor environment, thus modulating pro-tumor mechanisms such as drug resistance and inflammation." (PMID 41227296, 2025).
tumor (continued). "Immunohistochemistry analysis indicated that anti-CTSS staining in the glomerular mesangium and tubular epithelial cells of biopsied renal tissues from 25 IgAN patients were remarkably stronger than that in those from non-IgAN patients with trauma or tumor." (PMID 33912521, 2021). "Interestingly, it was observed that tumor cells increase the expression of cathepsin S, a protease that is pre-dominantly expressed by leukocytes, to cleave junctional adhesion molecules that maintain the BBB integrity and thus assist tumor cells to breach the BBB." (PMID 31396225, 2019). "In the present study, we show that cathepsin S is on the surface of tumour cells and that this localization can be exploited with a fully human IgG1 version of Fsn0503 (Fsn0503h) to induce ADCC, demonstrating the clinical potential of the engineered cathepsin S specific human antibody Fsn0503h." (PMID 22168338, 2011).
cancer (227 papers, 2003 to 2026). A tumor composed of atypical neoplastic, often pleomorphic cells that invade other tissues. "CTSS, one of the 11 members of the cysteine protease family, is closely associated with various pathological conditions, including in cancers." (PMID 40256740, 2025). "In the future, complementary studies involving the inoculation of HSC-3 cells into wild-type and cathepsin S-deficient nude mice would shed light on the contribution of stromal (macrophage)-supplied cathepsin S to cancer pain." (PMID 34572924, 2021). "The cysteine protease cathepsin S (CTSS) is one of a family of 11 cysteine cathepsin proteases, and has been found to be associated with a variety of pathologies, including cancer." (PMID 31346333, 2019). "As such, increased CTSS expression has been shown be associated with poor clinical features in a number of cancer types, as well as holding prognostic value with expression associated with poor outcome in others." (PMID 31346333, 2019). "Cathepsin S (CTSS) has previously been implicated in a number of cancer types, where it is associated with poor clinical features and outcome." (PMID 31346333, 2019). "Nevertheless, increased level of secreted CTSS or CTSB have been shown to be associated with metastasis in other cancer types." (PMID 27802179, 2016). "Increased circulating cathepsin S levels have been linked to increased risk of cardiometabolic diseases and cancer." (PMID 25128296, 2014). "Confocal analysis of cancer cell line models also support this association as cathepsin S was observed to localize to the cell surface membrane with intense staining restricted to specific regions." (PMID 22168338, 2011). "Furthermore, increased glycosylation levels for CTSs are reported in various cancers and represent a risk factor for the metastatic process." (PMID 41227296, 2025). "As far as we know, this is the first study that has shown an association between CTSS and the HDL3a and HDL3b subclasses, and the reduced apoptosis present in cancer could also be a consequence of this association." (PMID 39712508, 2024). "CTSS, which is a member of the cathepsin family of cysteine proteases, has been implicated in an important role in cancer development, was highly expressed in human cancer." (PMID 35436995, 2022). "CTSS has been found to be associated with a variety of biological functions in cancer." (PMID 35264209, 2022). "Among these CTSs, several cysteine proteinases have been reported to be associated with progression of cancers by regulating immune response although their functions are entirely different in different cancers." (PMID 34923982, 2021). "Cathepsin S is active in the extracellular environment of the cancer and associated neurons." (PMID 34572924, 2021). "Therefore, ER stress caused by the inhibition of cathepsin S sensitized cells to anti-cancer drug-mediated apoptosis through the modulation of apoptosis-related proteins rather than the induction of autophagy or the activation of JNK phosphorylation." (PMID 30120227, 2018). "In addition, the effects and mechanisms underlying CTSS blockade are well-studied in cancer and inflammation, but the effect of the pharmacological inhibition of CTSS in the brain remains unclear." (PMID 38725007, 2024). "Although cancer and normal cells exhibit differential CTSS expression levels, the compound lacks specificity for malignant cells." (PMID 40707961, 2025). "Transcriptomic data from the TCGA revealed that the mean CTSS expression was highest for CRC tissues among all evaluated cancer types." (PMID 40794185, 2025). "The precancerous microenvironment showed significant upregulation of zebrafish orthologues for MMP25 and CTSB, while orthologues for multiple MMPs and CTSs were upregulated in the cancer microenvironment." (PMID 39511408, 2025). "Studies have demonstrated that CTSS inhibition induces autophagy in various cancers, including lung, oral, and glioma cancers." (PMID 40794185, 2025).